PTTG1 (PTTG1 regulator of sister chromatid separation, securin)
Diseases named in the same sentence as PTTG1 in open-access papers (continued):
Sharing a sentence is not in itself a finding about the gene and the disease.
lymph node metastasis (8 papers, 2006 to 2026). "Lymph node metastasis also correlated with necrosis; however, logistic regression confirmed that PTTG1 score was independently associated with nodal involvement (p = 0.002), regardless of tumor size and necrosis." (PMID 41976385, 2026). "PTTG1 which expressed at very undetectable or low level in normal tissues, was shown to be highly expressed in a variety of cancers tissues: colorectal, ovarian, breast, colon and esophagus, what's more its expression was also associated with lymph node metastasis." (PMID 29190924, 2017). "It was reported in the literature that the high expression of PTTG1 was closely related to the pathological stage and lymph node metastasis." (PMID 33552118, 2020). "A higher PTTG1 expression significantly correlated with pathological stage and lymph node metastases." (PMID 32824814, 2020). "In contrast, a strong expression of PTTG-1 in patients with NSCLC was associated with a significant shorter survival, advanced lymph node metastases and distant metastases." (PMID 16426442, 2006). "Furthermore, the up-regulation of PTTG1 was positively correlated with lymph node metastasis." (PMID 29190924, 2017). "Next, we proceeded to explore the relationship between the expression of RHOV, ANLN, PTTG1, DLGAP5, and FAM83A with pathological stage and lymph node metastasis, and the results showed that the transcriptional expression of the five prognostic features progressively increased with the stage." (PMID 39144144, 2024). "In addition, PTTG1 expression was statistically different among the groups with or without regional lymph node metastasis (p < 0.0001)." (PMID 30911297, 2019).
multiple myeloma (8 papers, 2008 to 2024). "Knockdown of Pttg1 significantly inhibited the proliferation of myeloma cells in vitro, with an associated decrease in the expression of mitosis-related genes, and slowed tumour development in vivo." (PMID 26445238, 2015). "Interestingly, gene expression profiling studies have shown that the presence of chromosomal instability in newly diagnosed myeloma patients is associated with a gene expression profile that includes upregulation of PTTG1." (PMID 26445238, 2015). "As high PTTG1 expression in MM patients correlates with increased expression of cell cycle- and proliferation-associated genes, we next examined whether Pttg1 may play a role in modulating cell cycle progression and proliferation in murine myeloma plasma cells." (PMID 26445238, 2015). "KLF10 attenuates the nuclear translocation of beta-catenin, inhibits the expression of PTTG1, and then decreases the proliferation of multiple myeloma." (PMID 35743973, 2022). "Concordantly, PTTG1 overexpression results in poor prognoses of patients with myelomas, clear cell renal cell carcinoma, and adrenocortical cancer 65-67." (PMID 33173433, 2020). "The purpose was to investigate the presence/rate of expression of PTTG-1 in multiple myeloma patients." (PMID 18384692, 2008). "Furthermore, knockdown of Pttg1 decreases cellular proliferation in vitro and reduces myeloma tumour burden in vivo in the KaLwRij model of MM." (PMID 26445238, 2015). "Additionally, we investigated the effect of short hairpin ribonucleic acid (shRNA)-mediated PTTG1 knockdown on the proliferation of the murine myeloma plasma cell line 5TGM1 in vitro and in vivo." (PMID 26445238, 2015). "Notably, our Pttg1 knockdown studies in the KaLwRij-derived 5TGM1 myeloma plasma cell line resulted in a reduction in cellular proliferation in vitro, as well as decreased tumour development in vivo." (PMID 26445238, 2015). "Importantly, Pttg1 knockdown in myeloma cells leads to a 40 % reduction in DEPDC1 expression." (PMID 26445238, 2015). "We have previously identified pituitary tumour transforming gene 1 (Pttg1) as a gene that is significantly upregulated in the haematopoietic compartment of the myeloma-susceptible C57BL/KaLwRij mouse strain, when compared with the myeloma-resistant C57BL/6 mouse." (PMID 26445238, 2015). "Downregulation of KLF10 was found in multiple myeloma tissues compared to normal groups, whereas overexpression of KLF10 mitigated the proliferation of multiple myeloma cells by controlling PTTG1 expression." (PMID 35743973, 2022). "We analyzed the PTTG-1 expression at the transcriptional and the protein level, by PCR, immunocytochemical methods, Dot-blot and ELISA performed on patient's sera in 19 multiple myeloma patients, 6 different multiple myeloma cell lines and in normal human tissue." (PMID 18384692, 2008).
pancreatic cancer (8 papers, 2021 to 2026). "PTTG1 (pituitary tumor‐transforming gene 1) encodes a small molecule protein, securin, which promotes pancreatic cancer cell proliferation by regulating c‐myc." (PMID 41523581, 2026). "Then, the effect of PTTG1 on pancreatic cancer progression was investigated, and the high expression of PTTG1 was linked to poorer overall survival and disease-free survival in patients with pancreatic cancer." (PMID 38465336, 2024). "The Cancer Genome Atlas Program (TCGA) data showed that higher expression of PTTG1 was associated with higher clinical stages and worse prognosis of pancreatic cancer." (PMID 37243239, 2023). "Thus, PTTG1 is highly expressed in pancreatic cancer tissues, which is negatively associated with poor prognosis." (PMID 38465336, 2024). "In addition, higher expression of PTTG1 was also significantly associated with a reduction in PFS in pancreatic cancer." (PMID 37243239, 2023). "To evaluate the value of PTTG1 in predicting the prognosis of pancreatic cancer patients, we analyzed the association between its expression and overall survival (OS), disease-free survival (DFS), progression-free survival (PFS), and disease-specific survival (DSS) in the TCGA cohort." (PMID 37243239, 2023). "Overexpression of PTTG1 was observed in pancreatic cancer tissue, and the higher the histological grade of the cancer, the higher the level of PTTG1." (PMID 40072059, 2025). "In pancreatic cancer, PTTG1 overexpression has been described and correlated with a higher histological grade of pancreatic cancer." (PMID 40072059, 2025). "This study aimed to clarify the role of pituitary tumor-transforming gene 1 (PTTG1) in proliferation, migration, invasion, and aerobic glycolysis of pancreatic cancer cells, and evaluate the potential of PTTG1 as a therapeutic target." (PMID 38465336, 2024). "Panc1 cells with PTTG1 knockdown and Mia-PaCa2 cells with PTTG1 overexpression were used to evaluate the proliferation, migration, invasion, and aerobic glycolysis of pancreatic cancer." (PMID 38465336, 2024). "The analysis of PTTG1 expression levels using the GEPIA website revealed that PTTG1 was indeed highly expressed in pancreatic cancer tissues." (PMID 38465336, 2024). "In conclusion, PTTG1 induces proliferation, migration, and invasion, and promotes aerobic glycolysis in pancreatic cancer cells via regulating c-myc, demonstrating the potential of PTTG1 as a therapeutic target." (PMID 38465336, 2024). "Western blot results indicated that PTTG1 expression in pancreatic cancer cells including Sw1990, Capan1, Panc1, and Mia-PaCa2 is significantly higher than that in HPNE, which is the normal cell line." (PMID 38465336, 2024). "Our results showed that PTTG1 expression is upregulated in pancreatic cancer, which promoted cell proliferation." (PMID 38465336, 2024). "Multiple reports have demonstrated that PTTG1 expression is elevated in pancreatic cancer tissues, suggesting its involvement progression of this disease." (PMID 38465336, 2024). "High expression of PTTG1 was related to poor overall survival and disease-free survival in patients with pancreatic cancer." (PMID 38465336, 2024). "This study demonstrated that PTTG1 is upregulated in pancreatic cancer, and PTTG1 expression positively regulates the proliferation, migration, invasion, and aerobic glycolysis of pancreatic cancer through regulating c-myc." (PMID 38465336, 2024). "In conclusion, overexpression of PTTG1 promotes cell proliferation, migration, and invasion of pancreatic cancer, and it also regulates c-myc-mediated aerobic glycolysis." (PMID 38465336, 2024). "In summary, overexpression of PTTG1 promotes the proliferation of pancreatic cancer cells by promoting cell cycle progression and interacting with other proteins involved in cell cycle regulation." (PMID 38465336, 2024). "PTTG1 is overexpressed in human pancreatic cancer tissues, but its role in pancreatic cancer is still unclear." (PMID 38465336, 2024).
pancreatic cancer (continued). "PTTG1 increases the migration and invasion of pancreatic cancer cells by regulating various signaling pathways." (PMID 38465336, 2024). "PTTG1 has been reported to be overexpressed in several cancers, so we examined the PTTG1 expression in pancreatic cancer." (PMID 38465336, 2024). "In this study, PTTG1 was confirmed to be highly expressed in pancreatic cancers, which is consistent with the previous findings." (PMID 38465336, 2024). "Using comprehensive analysis of the data of normal pancreatic tissues and pancreatic cancer tissues, we found that the expression of PTTG1 was positively correlated with CXADR." (PMID 37243239, 2023). "In summary, PTTG1 enhanced OAd5 transduction into pancreatic cancer cells by increasing CXADR expression on the cell surface." (PMID 37243239, 2023). "In summary, PTTG1 enhances OAd5 entrance into pancreatic cancer cells through increasing CXADR expression on the cell surface." (PMID 37243239, 2023). "Due to the potential of oncolytic viruses in cancer treatment, we tried to further explore the impact of PTTG1 on the efficiency of OAd5 in killing pancreatic cancer cells." (PMID 37243239, 2023). "As a result, the expression of CXADR was positively correlated with PTTG1 in pancreases and pancreatic cancer tissues." (PMID 37243239, 2023). "The analysis revealed that PTTG1 expression was higher in pancreatic cancer tumor tissues than in normal ones." (PMID 37243239, 2023). "Higher expression of PTTG1 was significantly associated with shorter OS and DSS in pancreatic cancer." (PMID 37243239, 2023). "This study showed that PTTG1 is upregulated in pancreatic cancer." (PMID 38465336, 2024). "Moreover, in vivo studies using mouse models of pancreatic cancer have demonstrated that PTTG1 promotes tumor growth, metastasis, and invasion." (PMID 38465336, 2024). "Therefore, altogether, these results suggested that PTTG1 overexpression promotes the proliferation of pancreatic cancer cells." (PMID 38465336, 2024). "In addition, several in vitro studies have shown that PTTG1 is overexpressed in pancreatic cancer cell lines, including BxPC-3, AsPC-1, and Panc-1 cells." (PMID 38465336, 2024). "In summary, overexpression of PTTG1 accelerates migration and invasion of pancreatic cancer cells." (PMID 38465336, 2024). "Inhibition of PTTG1 expression or activity can suppress the metastasis of pancreatic cancer cells, suggesting that PTTG1 may be a potential target for the development of novel anticancer therapies." (PMID 38465336, 2024). "PTTG1 expression in pancreatic cancers was analyzed using the GEPIA databank." (PMID 38465336, 2024). "Inhibition of PTTG1 expression or activity can suppress the proliferation of pancreatic cancer cells, suggesting that PTTG1 may be a potential target for the development of novel anticancer therapies." (PMID 38465336, 2024). "At 24 h post-infection, nearly 80% of wild-type-infected cells were in S-phase; we hypothesized whether PTTG1 remarkably increased OAd5 entrance into pancreatic cancer cells." (PMID 37243239, 2023). "Furthermore, the expression of PTTG1 was closely related to the clinical stage, being higher in pancreatic cancer patients with relatively high stages." (PMID 37243239, 2023). "Furthermore, we predicted potential ICB response with the TIDE algorithm in pancreatic cancer, finding that the ICBs’ efficiency is poor in the PTTG1 high group." (PMID 37243239, 2023). "The analysis indicates that PTTG1 is involved in disease progression in pancreatic cancer." (PMID 37243239, 2023). "In the process of using oncolytic virus to treat pancreatic cancer, if priority is given to patients with a high expression of PTTG1 in tissues, it may provide additional benefits." (PMID 37243239, 2023). "We wondered whether ICBs could treat pancreatic cancer patients with high PTTG1 expression, so we analyzed the ICBs’ response with the TIDE algorithm in pancreatic cancer." (PMID 37243239, 2023).
pancreatic cancer (continued). "We first assessed PTTG1 expression in pancreatic cancer from the TCGA database." (PMID 37243239, 2023). "Additionally, we found that higher expression of PTTG1 was significantly associated with shorter OS, DFS, PFS, and DSS in pancreatic cancer." (PMID 37243239, 2023). "We found that overexpression of PTTG1 predicts a higher grade of pancreatic cancer." (PMID 37243239, 2023). "Therefore, treating pancreatic cancer patients with high PTTG1 expression is difficult using gemcitabine and 5-FU." (PMID 37243239, 2023). "Therefore, knockdown of PTTG1 inhibits the proliferation of pancreatic cancer cells." (PMID 38465336, 2024). "Targeting PTTG1 may be a promising strategy for the treatment of pancreatic cancer." (PMID 38465336, 2024). "Thus, PTTG1 may be a valuable marker for the severity of pancreatic cancer." (PMID 40072059, 2025). "The results indicate that chemotherapy and ICBs are not suitable remedies in pancreatic cancer patients with high PTTG1 expression, and we should explore alternatives for treating PAAD." (PMID 37243239, 2023). "The in vitro experiment proved that PTTG1 could improve the expression level of CXADR on the surface of pancreatic tumor cells, so we further assessed CXADR expression in pancreatic cancer from the TCGA database." (PMID 37243239, 2023). "Because OAd5 mainly replicates 24–48 h after transduction, the results indicate that PTTG1 might increase OAd5 entrance into pancreatic cancer cells, but it does not play a role in its replication." (PMID 37243239, 2023). "Based on our research, both chemotherapy and ICBs might not be promising treatments for pancreatic cancer patients with high PTTG1 expression." (PMID 37243239, 2023). "However, PTTG1 has not been extensively studied in pancreatic cancer." (PMID 37243239, 2023). "This also explains why the expression level of PTTG1 is higher in tumor tissue of patients in higher grades, while CXADR is not related to the grade of pancreatic cancer." (PMID 37243239, 2023).
bladder cancer (7 papers, 2007 to 2024). "Pituitary tumor transforming gene-1 (PTTG1) transcription factor is identified as carcinogenic and associated with tumor invasiveness, but its role in bladder cancer (BLCA) remains obscure." (PMID 35768832, 2022). "In vitro studies have shown that PTTG1 promotes cell cycle progression and increases the proliferation of bladder cancer cells." (PMID 38465336, 2024). "We also analyzed PTTG1 levels in the 45 pairs of bladder cancer tissues and adjacent normal bladder tissues." (PMID 27893422, 2017). "Real-time RT-PCR suggested PTTG1 was significantly upregulated in bladder cancer tissues compared to adjacent normal bladder tissues." (PMID 27893422, 2017). "Western blot analysis also suggested PTTG1 was upregulated in bladder cancer tissues compared to the normal bladder tissues." (PMID 27893422, 2017). "It has been shown that miR-146a inhibited bladder cancer progression by targeting PTTG1, which may be the target of bladder cancer therapy." (PMID 28579964, 2017). "Both miR-146a-3p and PTTG1 could be considered as two promising targets for bladder carcinoma treatment in the future." (PMID 27893422, 2017). "However, the role of PTTG1 in bladder cancer (BC) hasn't yet been characterized well." (PMID 27893422, 2017). "Also Plk1 has been reported to be regulated by E2F3 in bladder cancer cells in addition to known E2F3 targets such as Cyclin A and novel targets including pituitary tumor transforming gene 1 (PTTG1), and Caveolin-2." (PMID 19883508, 2009).
breast tumors (5 papers, 2008 to 2025). "Through integrative analyses of transcriptomic datasets, we identified a germline-associated molecular signature, with CCNB1, CCNB2, PTTG1, RACGAP1, and UBE2C emerging as core EGT gene clusters markedly upregulated in breast tumors." (PMID 41009526, 2025). "The relative gene expression analysis of seven PGC-associated genes, including CCNB1, CCNB2, FEN1, MCM4, PTTG1, RACGAP1, and UBE2C, was conducted on the samples of breast tumors compared to healthy mammary tissues." (PMID 41009526, 2025). "The stromal cells of breast tumors show a marked expression of genes such as PTTG1 and RACGAP1." (PMID 41009526, 2025). "Moreover, in human breast tumors, PTTG1 protein levels were down-regulated and the reduction was significantly correlated with the tumor grade." (PMID 26320179, 2015). "The result of our experience has highlighted a significant overexpression of five CCNB1, CCNB2, PTTG1, RACGAP1, and UBE2C genes in breast tumors compared to the normal tissues (p-value < 0.05)." (PMID 41009526, 2025). "The average expressions of these genes in breast tumor samples compared to healthy mammary biopsies (tumor/healthy) were as follows: CCNB2 (0.483/−0.869), CCNB1 (0.262/−0.472), PTTG1 (0.398/−0.719), RACGAP1 (0.338/−0.609), and UBE2C (0.565/−1.016)." (PMID 41009526, 2025). "The dual roles of chemokines in the senescence context are nicely exemplified by a study on human pituitary tumor-transforming gene 1 (PTTG-1)-driven expression of CXCL1 and CXCL8 in breast tumor cells." (PMID 32582148, 2020). "In our experiments using the breast tumor cell line MCF-7, we showed that insulin and IGF-1 regulate the expression of PTTG1 primarily through the activation of phosphoinositol-3-kinase (PI3K)/AKT cascade." (PMID 19014669, 2008). "In addition, 6/7 PC-CIN genes (CEP55, UBE2C, MELK, TPX2, PTTG1, and CDCA3) were also found to be among the top DEGs identified through comparison of high aneuploidy versus low aneuploidy breast tumors in TCGA." (PMID 32380981, 2020).
adenoma (4 papers, 2011 to 2019). A neoplasm arising from the epithelium. "Array data mining found that genes such as Ccnb1, Igfbp3, Nusap1, Pttg1, Racgap1, Top2a, Tpx2, which are associated with the aggressive behaviour of various human tumors, including PAs, and proto-oncogenes such as Ect2, Kit, Kras, Lyn, Ret are up-regulated in rat adenomas." (PMID 23756599, 2013). "Some genes or gene families we found up-regulated in MENX adenomas had previously been identified in human aggressive-invasive PAs, e.g., PTTG1, RACGAP1, CCNB1, CENPE, AURKB." (PMID 23756599, 2013).
clear cell renal cell carcinoma (4 papers, 2017 to 2025). "In aggressive clear cell renal cell carcinoma, the ECT2 expression correlated with pituitary tumor-transforming 1 (PTTG1) expression and poor clinical outcomes, suggesting a possible downstream molecular mechanism whereby ECT2 promoted cancer malignancy." (PMID 28362321, 2017). "In Beroukhim Renal Statistics, PTTG1 over-expression was found in non-hereditary clear cell renal cell carcinoma tissues compared with normal tissues with a fold change of 5.231 (p=7.53E−10)." (PMID 33845847, 2021).